TLR3 (toll like receptor 3)
Diseases named in the same sentence as TLR3 in open-access papers (continued):
Sharing a sentence is not in itself a finding about the gene and the disease.
asthma (continued). "Our objective was to Characterize a model of peripheral blood mononuclear cells (PBMCs) of patients with severe asthma (SA) and its response to the TLR3 agonist Poly I:C using two single-cell methods." (PMID 33902571, 2021). "We therefore aimed to investigate the effect of vitamin D3 treatment on viral-induced TLR3 responses in Bronchial Smooth Muscle Cells (BSMCs) as a mechanism contributing to pulmonary fibrosis in asthma and COPD." (PMID 34512638, 2021). "While Addition of 1,25D3 to polyI:C-stimulated BSMCs significantly decreased TLR3 expression, in asthma (1.743 ± 0.6387-fold decrease, p < 0.05) and COPD (4.495 ± 0.6318-fold decrease, p < 0.05) as compared to control groups." (PMID 34512638, 2021). "Stimulation of BSMCs with polyI:C (5 ug/ml) for 24 hours significantly induced mRNA expression of TLR3, in asthma (6.047 ± 0.924-fold increase, p < 0.05) and COPD (9.878 ± 0.779-fold increase, p < 0.001) as compared to control groups." (PMID 34512638, 2021). "In the present study, we have demonstrated the effect of vitamin D3 supplementation on viral-induced TLR3 responses in Bronchial Smooth Muscle Cells (BSMCs), as a mechanism contributing to pulmonary fibrosis in asthma and COPD." (PMID 34512638, 2021). "Nevertheless, there are several mucosal molecules/pathways that are currently under investigation as potential therapeutic targets for type 2 low or mixed type of asthma, these include IL‐6 and TLR‐3,4,7." (PMID 33133517, 2020). "Toll-like receptor 3(TLR-3), TLR-9, DECTIN-1 variants were shown to be associated with severe asthma with fungal sensitization (SAFS) induced by Aspergillus fumigatus in a Caucasian older cohort." (PMID 31824491, 2019). "Previously, we reported that ex vivo study of IFN-β– and IFN-λ–deficient bronchial epithelial cells in patients with severe asthma, baseline expression of TLR3 mRNA, and rhinovirus induction of TLR3, MDA5, and RIG-I mRNA were impaired." (PMID 29698627, 2019). "Asthma-like exacerbations were thus produced by a sequential combination involving HDM-induced lung inflammation followed by stimulation with the TLR3 agonist poly(I:C)." (PMID 28415826, 2017). "A recent study using a mouse model also suggested that TLR3 contributes to the exacerbation of virus-induced asthma." (PMID 24886842, 2014). "Tlr3 contributes to asthma exacerbations in mice and a study in a murine macrophage cell line suggested a pro-inflammatory role of Tlr4 and 5 in the disease." (PMID 24735374, 2014). "In mild asthma, Tlr3 expression was significantly decreased in allergen-sensitized and challenged mice when compared to control mice." (PMID 23781124, 2013). "In severe asthma, Tlr3 expression was significantly lower in sensitized and challenged mice but not in control, sensitized only, and challenged only mice." (PMID 23781124, 2013). "To confirm that up-regulated TLR3 played an important part in asthma development, we interfered TLR3 expression with specific short-hairpin RNA (shRNA) plasmid." (PMID 21364926, 2011). "Rhinovirus (RV) infections activate TLR3-mediated responses in the respiratory tract, exacerbating asthma and chronic obstructive pulmonary disease." (PMID 22039520, 2011). "Furthermore, studies have also revealed the important role of the TLR3/NF-κB/IRF3 signaling pathway in the progression of viral-induced asthma." (PMID 40672946, 2025). "In addition, ISS from asthma patients also had an activation effect on TLR3, TLR7, and TLR8, which play crucial roles in immune regulation." (PMID 39950864, 2025). "Excessive TLR3-mediated inflammation may play a key role in promoting asthma exacerbation and fibrosis, with bronchial smooth muscle cells (BSMCs) being one of the major contributors to asthma airway remodeling." (PMID 37577440, 2023). "For this reason, NLRP3 which regulates pyroptosis-induced asthma requires to be further studied, and TLR3/NLRP3/NF-κB/IRF3 signaling inhibition could be an anti-inflammatory strategy in airway epithelial injury." (PMID 36213326, 2022).
asthma (continued). "Interestingly, we observed a higher grade of VDR and TLR3 activation in BSMCs from subjects with asthma and COPD when compared with controls." (PMID 34512638, 2021). "Although TLR3 has a major role in viral-induced immune responses, excessive TLR3 inflammatory responses may play a key role in promoting exacerbations and fibrosis in asthma and COPD." (PMID 34512638, 2021). "Delayed IFN production could result from reduced antigen recognition, as has been reported in samples from children with severe asthma where reduced TLR3, RIG, and MDA5 expression were observed." (PMID 32499788, 2020). "Finally, we investigated the potential of CRISPR-based approaches to functionally evaluate H3K27ac-asthma landscape in vitro by identifying guide-RNAs capable of targeting acetylation to asthma DERs and inducing gene expression (TLR3)." (PMID 33362848, 2020). "We identified gRNAs that successfully targeted acetylation to asthma DERs at TLR3 and found that gene expression could be induced in an acetylation-specific manner." (PMID 33362848, 2020). "Coupled with no apparent association of TLR3 to the development or severity of either asthma or allergy, it is unlikely to be developed further in the future." (PMID 33281825, 2020). "However, as there are limited studies upon the actions of TLR3 activation or inhibition in asthma and allergy, a conclusion cannot be drawn about either strategies inclusion in AIT." (PMID 33281825, 2020). "This study identifies two novel components of the inflammatory pathway that regulates the immune response following RV infection and TLR3 stimulation, highlighting TN-C release and pro-inflammatory sEVs in the airway as relevant to the biology of virally induced exacerbations of asthma." (PMID 31497021, 2019). "This study highlights an important interaction between IL-17A and TLR3 signaling in excessive airway inflammation, and control of IL-17A/TLR3-mediated NF-κB/IRF3 activation may be a novel therapeutic target to prevent exacerbation of asthma." (PMID 26418032, 2015). "TLR3 recognises dsRNA derived from respiratory viruses and activates nuclear factor-κB, which increases interferon-γ signalling in other cells and transforms airway inflammation into asthma." (PMID 25326706, 2014). "In a recent paper it was shown that regulation of TLR3 is connected with asthma exacerbations." (PMID 23882263, 2013). "Abnormal activation of the TLR3 signaling pathway and excessive activation of its downstream signaling factor TRIF can trigger the recruitment of local inflammatory cells and excessive synthesis of proinflammatory mediators, thereby causing various inflammatory diseases including asthma." (PMID 40672946, 2025). "The present study was carried out to complement this exploratory study series by evaluating whether the TLR3 rs3775291, TLR4 rs4986790, TLR7 rs179008, TLR8 rs2407992, TLR9 rs187084, and TLR10 rs4129009 polymorphisms are associated with post-bronchiolitis asthma." (PMID 28592890, 2017). "Therefore the role of TLR3 in asthma is still obscure for researchers." (PMID 21364926, 2011). "TLR3 monoclonal antibody, which targets PRRs as a TLR antagonist, was evaluated in patients with asthma." (PMID 36077310, 2022). "Besides, more detailed basic and clinical investigations through systemic inhibition studies such as knock-down or knock-out models are required to assess whether overexpression of TLR3/NLRP3/NF-κB/IRF3 signaling could reverse the protective effect of CAD on asthma." (PMID 36213326, 2022). "Therefore, we are devoted to exploring the effects of CAD on pyroptosis and the TLR3/NLRP3/NF-κB/IRF3 signaling pathway in OVA/RSV-induced asthma mouse models, which may contribute to promoting understanding of CAD in the treatment of acute asthma with RSV infection." (PMID 36213326, 2022). "In our study, the levels of TLR3, p-P65, p-IκBα, and IRF3 were clearly increased in lung tissues of asthma mice and LPS-mediated 16HBE cells." (PMID 36213326, 2022).
asthma (continued). "Our findings indicated that pro-inflammatory and pro-fibrotic mediators are increased at the baseline in BSMCs from both asthma and COPD, and that TLR3 agonist polyI:C, significantly upregulated IL-6, IFN-β1, CCL2, FN1 and COL1A1 expressions in BSMCs." (PMID 34512638, 2021). "Many other pathways were also identified that are regulated by IL-13 and relevant to asthma pathogenesis (e.g. CCL17, CCL26, CTGF, FCER1A, KITLG, MUC2, NOS2, TLR3)." (PMID 29367592, 2018). "Nevertheless, a recent study has been reported that application of TLR2, TLR3, TLR4 and TLR7 agonists all show a protective effect for asthma." (PMID 21364926, 2011). "All these findings illustrate that TLR3 and TLR7 in immune organs play a vital role in the development of asthma." (PMID 21364926, 2011). "The expression levels of IL17RA, IL4RA, integrin β2, CCR3, FCER1A, TGFB1, TLR‐3, TLR‐7, and TLR‐9 in eosinophils treated with IL‐17 for 3 h were higher for normal individuals than for patients with asthma." (PMID 39575691, 2024). "Generally, these results indicated that apoptosis and pyroptosis played an important role in RSV-infected asthma mice and LPS-mediated 16HBE cells, and CAD potential inhibits the TLR3/NLRP3/NF-κB/IRF3 signaling pathway and subsequently suppresses airway inflammation and pyroptosis." (PMID 36213326, 2022). "Dupilumab might also improve antiviral immune responses in patients with T2-high asthma because IL-4 and IL-13 impaired viral-induced IFN production and TLR3 expression." (PMID 36077310, 2022). "Moreover, some researchers have demonstrated the crucial role of the TLR3/NF-κB/IRF3 signaling pathway, which is activated by the inflammatory cytokines during the progress of virus-induced asthma." (PMID 36213326, 2022). "Interestingly, simultaneous engagement of TLR3 and TLR7 by viral components prevented airway hyperresponsiveness and suppressed established asthma." (PMID 29867994, 2018). "TLR3 expression in asthma is not impaired, and blocking the receptor in mice does not have a significant effect in reducing viral replication." (PMID 30345002, 2018). "In viral-induced exacerbation of asthma, however, the part of IL-17A and the interplay between IL-17A and TLR3 activation have not been fully elucidated." (PMID 26418032, 2015). "However, no direct associations between Tlr3 and Nod1 expression and function and asthma have been reported yet, and whether the decreased mRNA expression of Tlr3 and Nod1 caused by the chronic inflammatory status of the animals is pro-inflammatory or anti-inflammatory is also unknown." (PMID 24735374, 2014). "Two key pathogens known to be involved in asthma exacerbation, namely RSV and S. pneumonia, are recognised by TLR3 and TLR4 respectively, suggesting these PRRs may play a role in exacerbation." (PMID 25089623, 2014). "However, no direct associations between Tlr3 expression and function and asthma have been reported yet, and whether the decreased mRNA expression of Tlr3 caused by the chronic inflammatory status of the animals is proinflammatory or anti-inflammatory is also unknown." (PMID 23781124, 2013). "If this were true in humans, then antagonists against TLR3 and MDA5 could provide potential therapeutic agents in the treatment of virus-induced asthma exacerbations." (PMID 21637773, 2011). "Additionally, CAD and CAD-contained serum attenuated the up-regulated expressions of Bax, Cleaved caspase-3, NLRP3, ASC, Cleaved caspase-1, GSDMD-N, IL-18, IL-1β, TLR3, p-P65, p-IκBα, and IRF3 but increased Bcl-1 and GSDMD levels in the asthma mice and LPS-induced 16HBE cells, respectively." (PMID 36213326, 2022). "Agonists of intracellular TLRs such as TLR3 agonist poly(I:C) and TLR7/8 agonist imidazoquinoline promote activation of Th1 immune responses; the TLR9 synthetic agonists are being investigated for cancer immunotherapy, asthma and allergy therapy, and vaccine adjuvants." (PMID 23151919, 2012).
asthma (continued). "The same study suggested that TLR3 systemically modulated disease development in a rat asthma model by reducing serum IgE release via IL4 down-regulation, which may provide a vital clue for further research in asthma pathogenesis and suggest a new target for asthma treatment." (PMID 23882263, 2013). "Primary BSMCs from patients with asthma (n=4), COPD (n=4), and healthy control subjects (n=6) were treated with polyinosinic: polycytidylic acid (polyI:C), TLR3 agonist in the presence or absence of vitamin D3 (1,25D3)." (PMID 34512638, 2021). "Interestingly, treatment with CNTO3157, an inhibitory monoclonal antibody to Toll-like receptor 3 (TLR3), failed to prevent an RV-induced fall in FEV1 and airway symptoms in subjects with asthma but ameliorated symptoms in healthy subjects." (PMID 30373568, 2018).
hepatocellular carcinoma (55 papers, 2008 to 2025). A malignant tumor that arises from hepatocytes. "The pro-inflammatory microenvironment promoted by TLR3 activation of NF-κB may also be a prognostic risk factor in cancer progression, as observed in many cancers, such as head and neck squamous cell carcinoma, colon carcinoma, and hepatocellular carcinoma." (PMID 39988665, 2025). "Several studies demonstrated that loss of function TLR3 polymorphisms are associated with an increased risk of head and neck squamous cell carcinoma (HNSCC), hepatocellular carcinoma (HCC) and CRC." (PMID 37112730, 2023). "TLR3 senses the HCV through the detection of dsRNA intermediates in infected hepatoma cells and activates the TLR3-signaling cascade, resulting in the production of type I and II IFNs and limiting the virus replication." (PMID 35965577, 2022). "The FDA has granted the orphan drug designation to the TLR3 agonist poly(I:C)-expressing rabies virus-based vaccine YS-ON-001 for the treatment of hepatocellular carcinoma and pancreatic cancer." (PMID 35148751, 2022). "In patients with hepatocellular carcinoma (HCC), neuroblastomas or esophageal squamous cell carcinoma, TLR3 was associated with greater survival, while its expression was significantly associated with poor overall survival in patients with resectable gastric tumors or breast cancer." (PMID 31582772, 2019). "For example, overexpression of HBV polymerase in a hepatoma cell line (HepG2/HepG2.215) blocks downstream signals of the pathogen recognition receptors TLR3 and retinoic acid–inducible gene 1 (RIG-I)." (PMID 27121087, 2016). "Overall, these results showed involvement of RIG-I and TLR3 pathways in restricting HEV replication in hepatoma cells." (PMID 27230536, 2016). "The only continuous cell lines that support robust HCV replication are derived from Huh-7 human hepatoma cells, which like many transformed hepatocytes are TLR3 null." (PMID 23717201, 2013). "Similar to human hepatoma cells, the expression of wPD-L1 was upregulated by TLR3 (14.9-fold) and TLR4 (4.3-fold) ligands, woodchuck IFN-α (4.3-fold) and -γ (4.6-fold) in PWHs." (PMID 22022563, 2011). "We demonstrated a minimal gain of permissiveness for HAV replication in hepatocyte-derived cells in which TLR3 or TRIF expression was depleted, and a reduction in viral antigen expression in hepatoma cells with active TLR3 signaling." (PMID 21931545, 2011). "Similarly, studies have shown that TLR3 expression correlates with apoptosis, proliferation, and angiogenesis in hepatocellular carcinoma, and serves as a prognostic biomarker in renal clear cell carcinoma." (PMID 40847033, 2025). "Similarly, the combination of a TLR3 agonist with sorafenib can hinder the advancement of hepatocellular carcinoma through the activation of NK and CD8+ T cells." (PMID 40406122, 2025). "Similarly, TLR3 pathways seem poorly functional in hepatoma cells, having prompted researchers to ectopically express TLR3 in these cells." (PMID 34831243, 2021). "Dysfunctional RIG-/MDA5 and TLR3 pathways have been reported in human hepatoma cells." (PMID 34831243, 2021). "Additionally, the activation of TLR3 following the poly(I:C) treatment resulted in a rise in cell death in the TLR3+ SNU182 hepatocellular carcinoma cell line while also enhancing stimulation of NK cells and their cytotoxicity by 4-fold in vitro." (PMID 32211442, 2020). "The expression of TLR3 is related to apoptosis, proliferation and angiogenesis of hepatocellular carcinoma, which could predict the prognosis." (PMID 32912361, 2020). "TLR3 also plays an important role in HBV-related hepatocellular carcinoma." (PMID 32912361, 2020). "Additionally, knockdown of TLR3 in Huh-7 (human hepatocellular carcinoma) cells or knockout of TLR3 in macrophages resulted in higher DENV (serotype 1) infection, compared to the control cells." (PMID 31652496, 2019).